CFB (complement factor B)
Diseases named in the same sentence as CFB in open-access papers (continued):
Sharing a sentence is not in itself a finding about the gene and the disease.
macular degeneration (2 papers, 2016 to 2020). Loss of vision in the central portion of the retina (macula), secondary to retinal degeneration. "Interestingly, seven genes associated with macular degeneration (CFH, C3, C2, CFHR5, CFB and CFHR4, CFHR1) also form a statistically significant module in liver (p value < 10−26, z score = 10.85)." (PMID 27748412, 2016).
malaria (2 papers, 2016 to 2018). Malaria is a serious and sometimes fatal disease caused by a parasite that commonly infects a certain type of mosquito which feeds on humans. "It was observed that the levels of Complement C3 and Complement C4-B, Complement C5, Complement C9, Complement factor B and Complement C1q subcomponent subunit C were significantly elevated in malaria plasma MPs compared to controls." (PMID 28352210, 2016). "Other cellular proteins correlating with PF3D7_1460800 included alpha-1-B glycoprotein (A1BG), complement factor B (CFB), and CD14, which were previously reported to be differentially expressed in malaria patients." (PMID 29425228, 2018).
Myocardial fibrosis (2 papers, 2012 to 2023). "Although the different TGF-β isoforms have similar activating effects on cFB in vitro, their relative roles in the development of myocardial fibrosis in vivo are still controversial." (PMID 37834293, 2023). "The multifunctional cytokines of the TGF-β family are by far the most extensive activators of cFB and the role of their downstream signalling pathways for the development of myocardial fibrosis in HCM will be discussed in detail in the following sections." (PMID 37834293, 2023). "In a pressure-overload model in rats, cFB activation and myocardial fibrosis coincided with increased TGF-β gene expression, and these effects were also prevented by TGF-β neutralizing antibodies." (PMID 37834293, 2023). "Following this idea, single-cell RNA sequencing has allowed for a better insight into the interactions between the cardiomyocytes and cFB during the last few years and these studies have also been able to identify new key genes involved in HCM myocardial fibrosis." (PMID 37834293, 2023). "While blocking focal adhesion kinases reduces the development of myocardial fibrosis, it is not entirely clear whether this is attributed to the activation of cFB or the effects of focal adhesion kinase activation on other cells." (PMID 37834293, 2023).
nephritis (2 papers, 2016 to 2023). Inflammation of renal tissue. "Using mass spectrometry, we found an increase in the level of complement components C3, C4b, C5, C9, and CFB in the urine of patients with active nephritis." (PMID 37108355, 2023). "This activation results in the activation of complement factor B. Complement activation proceeds in association with the generation of C5a and MAC, producing nephritis." (PMID 29259684, 2016). "In a mouse model of nephritis induced with myeloperoxidase anti-neutrophil cytoplasmic antibody (MPO-ANCA), knocking out complement factor B and complement component C5 resulted in the absence of nephritis." (PMID 29259684, 2016).
nephrotic syndrome (2 papers, 2014 to 2026). A collection of symptoms that include severe edema, proteinuria, and hypoalbuminemia; it is indicative of renal dysfunction. "Susceptibility to bacterial infections in patients with a nephrotic syndrome has been attributed to decreased levels of IgG and the alternative complement factor B." (PMID 25330372, 2014).
pneumonia (2 papers, 2025 to 2026). An acute, acute and chronic, or chronic inflammation focally or diffusely affecting the lung parenchyma, caused by an infection in one or both of the lungs (by bacteria, viruses, fungi, or mycoplasma.). "Drug-target analyses suggested that modulation of the complement and coagulation cascades may benefit pneumonia patients with comorbid LC or COPD, highlighting CFB, SERPINA1, and SERPING1 as key candidates and pointing to monocyte-centered pathways as promising therapeutic directions." (PMID 41624060, 2026).
psychological distress (2 papers, 2018 to 2020). "There, we found hemopexin, complement factor B, and clusterin, among others, to be positively associated with increased psychological distress in CWP." (PMID 32719459, 2020). "By interpreting the score plot in combination with the loading plot for HADSCWP, three of the proteins with highest VIP value were positively associated with psychological distress: complement factor B, complement C1r subcomponent, and hemopexin." (PMID 30555396, 2018). "Psychological distress in CWP was associated with plasma proteins related to immunity response and iron ion metabolism such as complement factor B, complement C1r subcomponent, and hemopexin." (PMID 30555396, 2018).
retinal degeneration (2 papers, 2017 to 2021). Degeneration of the retina. "The important function of the alternative pathway in retinal degeneration was also shown in CFB-deficient mice, which were protected from retinal degeneration by laser-induced choroidal neovascularization and cigarette smoke exposure." (PMID 28676742, 2017).
thrombotic microangiopathy (2 papers, 2021 to 2025). The syndromes of microangiopathic hemolytic anemia, thrombocytopenia, and variable signs of organ impairment, due to platelet aggregation in the microcirculation. "Recurrence risk and kidney allograft outcome in recipients with aHUS were associated with thrombotic microangiopathy and de novo CFB mutation." (PMID 34276651, 2021). "Patients with LN with thrombotic microangiopathy have stronger staining intensity and deposition of MBL, MASP1/3, CFB, CFD, C4d, and VWF." (PMID 41031884, 2025).
airway hyperresponsiveness (1 paper, 2020). "Prior research has shown that elevated levels of complement factor B (CFB) are associated with inflammation and airway hyperresponsiveness." (PMID 32759853, 2020).
Alzheimer disease (1 paper, 2021). A progressive, neurodegenerative disease characterized by loss of function and death of nerve cells in several areas of the brain leading to loss of cognitive function such as memory and language. "And lastly, another Alzheimer’s disease study has also demonstrated differential expression of CFB in relation to Alzheimer’s45." (PMID 33441605, 2021).
ankylosing spondylitis (1 paper, 2024). An autoimmune chronic inflammatory disorder characterized by inflammation in the vertebral joints of the spine and sacroiliac joints. "For example, mutations in CFB potentially confer protection against celiac disease but increase susceptibility to ankylosing spondylitis (AS) and UC." (PMID 39009607, 2024).
autoimmune hemolytic anemia (1 paper, 2019). Autoimmune hemolytic anemia (AIHA) is an autoimmune disorder in which various types of auto-antibodies are directed against red blood cells causing their survival to be shortened and resulting in hemolytic anemia. "The decrease in CFB is seen in many diseases including autoimmune hemolytic anemia, cirrhosis, chronic active hepatitis, acute glomerulonephritis, while an increase in CFB suggests a malignant tumor." (PMID 31366012, 2019).
benign papilloma (1 paper, 2018). "Chemically induced mouse cSCC and 8 cSCC cell lines showed significant upregulation of C3 and CFB (complement factor B) gene and protein expression compared to benign papilloma and normal human epidermal keratinocytes." (PMID 29423024, 2018).
Brain atrophy (1 paper, 2024). Partial or complete wasting (loss) of brain tissue that was once present. "Preliminary analyses in different cognitive groups demonstrated that the reduced CSF complement peptides C1q, C2, C5, and CFB were associated with longitudinal brain atrophy (i.e., ventricles, whole brain, middle temporal lobe, or fusiform gyrus) and cognitive decline in MCI participants." (PMID 38238858, 2024).
C3 glomerulonephritis (1 paper, 2024). "Iptacopan is a small-molecule inhibitor targeting complement factor B, showing positive therapeutic effects in the treatment of PNH, C3 glomerulonephritis, and other diseases." (PMID 38792150, 2024).
cataract (1 paper, 2024). Partial or complete opacity of the crystalline lens of one or both eyes that decreases visual acuity and eventually results in blindness. "The ratios of aqueous humour/plasma of C1q, C4, C4b, C3b/iC3b, C5, CFB, CFD, CFI, and CFH in the RVO patients were significantly higher than those in the cataract patients." (PMID 39587546, 2024).
celiac disease (1 paper, 2024). An autoimmune genetic disorder with an unknown pattern of inheritance that primarily affects the digestive tract. "For instance, CFB was observed to alleviate the risk associated with celiac disease (ORUKB: 0.46, ORFinGenn: 0.59) while RNF5 heightened the risk for celiac disease (ORUKB: 3.41, ORFinGenn: 3.74)." (PMID 39009607, 2024).
choroidal neovascularization (1 paper, 2021). An eye disorder described by the growth of new blood vessels that originate from the choroid through a break in the Bruch membrane into the sub–retinal pigment epithelium (sub-RPE) or subretinal space. "Using mouse models of laser-induced choroidal neovascularization (CNV) and oxygen-induced retinopathy (OIR), our study demonstrated an increase in CFB expression during pathological angiogenesis." (PMID 34502486, 2021).
cognitive decline (1 paper, 2024). "Besides, our study found that neuroimaging markers might mediate the associations between CSF complement proteins (C1q, C2, C5, CFB and clusterin) and cognitive decline." (PMID 38238858, 2024). "The direct impact of reduced CSF complement peptides C1q, C2, C5, and CFB on cognitive decline was also observed in the MCI participants." (PMID 38238858, 2024). "This study systematically investigated the association of CSF complement proteins (C1q, C2, C5, C6, C8B, and CFB) with cognitive decline, AD pathology and brain structures, as well as the mediation effects of regional brain structures on cognition." (PMID 38238858, 2024).
colon carcinoma (1 paper, 2022). "Also, in colon carcinoma tissues, multiple complement elements including C2, C5, complement factor B (CFB), complement factor I (CFI), CR4, complement component 4 binding protein (C4BPB), CD46, CD55, and CPN1 were significantly higher than that in normal tissues." (PMID 35173724, 2022).
complement deficiencies (1 paper, 2020). "Both rare monogenic traits, such as terminal complement deficiencies of C5-C9, CFD, CFB, CFI, and C3, and common polymorphisms in the CFH/CFHR3 region have been found in association with IMD." (PMID 32067109, 2020).
cutaneous squamous cell carcinoma (1 paper, 2021). "It has also been shown that CFB knockdown results in a significant decrease in proliferation in cutaneous squamous cell carcinoma." (PMID 34075561, 2021).
dementia (1 paper, 2026). Loss of intellectual abilities interfering with an individual's social and occupational functions. "A higher mass spectrometry signal that maps to both complement c2 and complement factor B proteins was associated with lower hazard for incident dementia (hazard ratio = 0.75, p < 3.1 x 10-4, ncases = 212 and ncontrols = 6,765) diagnosed up to 17 years after blood sampling." (PMID 41646675, 2026).
geographic atrophy (1 paper, 2022). "Clinical trials targeting proteins encoded by the AMD-associated genomic loci C3, CFB, CFI, CFH, and ARMS2/HTRA1 are currently ongoing, and a phase III clinical trial for C3 inhibition recently showed a modest reduction of lesion growth in geographic atrophy." (PMID 36108770, 2022).
giardiasis (1 paper, 2023). An infection of the small intestine caused by the flagellated protozoan giardia lamblia. "In the liver, proteins upregulated during giardiasis included vitronectin (P29788), Ly6/PLAUR domain protein (Q9D7S0), complement factor B (P04186), and mucin-13 (P19467)." (PMID 36675151, 2023).
heart failure (1 paper, 2022). Inability of the heart to pump blood at an adequate rate to meet tissue metabolic requirements. "Applying these 12 CFB genes to tSNE analysis we distinguished donors from heart-failure patients, but the most prevalent distinction was a separation of the heart failure patients into two sub-clusters." (PMID 35719864, 2022).
Hypercholesterolemia (1 paper, 2015). An increased concentration of cholesterol in the blood. "Six proteins including retinol-binding protein 4 (RBP4), transthyretin (TTR), gelsolin, haptoglobin, complement factor B (CFB) and CD5 antigen-like protein (CD5L) were identified to play imperative roles in lipid metabolism and inflammatory processes as a consequence of hypercholesterolemia." (PMID 27103892, 2015).
kidney cancer (1 paper, 2024). Primary or metastatic malignant neoplasm involving the kidney. "Thus, the blood level of complement factor B (P00751) in patients with kidney cancer increased 1.7-fold (р = 0.004); similar elevation was observed in patients in the kidney disease group (1.4-fold; p = 0.13)." (PMID 39896931, 2024).
kidney tumor (1 paper, 2021). "To further examine activation of the alternative complement pathway in podocytes of DKD kidneys, we stained renal biopsies from patients with DKD and adjacent healthy kidney tissues of kidney tumor patients with antibodies against CFB, C3d, C5b-9, and C5aR." (PMID 34622800, 2021).
male infertility (1 paper, 2023). The inability of the male to effect fertilization of an ovum after a specified period of unprotected intercourse. "A total of five proteins (PFS males) have been used as potential markers of male infertility, namely B2M, complement-3 (C3), CFB, VNN2, and CTSS." (PMID 37969811, 2023).
Microscopic hematuria (1 paper, 2021). Microscopic hematuria detected by dipstick or microscopic examination of the urine. "The clinical feature of either paternal CFB variant or maternal COL4A5 variant is just mild microscopic hematuria." (PMID 34349783, 2021).
minimal change disease (1 paper, 2022). "We investigated the deposition of Bb and CFB in renal specimens of patients with DN (n = 21), patients with minimal change disease (MCD; n = 10), and HCs (n = 10) by immunohistochemical staining to investigate complement AP activation in kidneys." (PMID 36546481, 2022).
multiple sclerosis (1 paper, 2024). A progressive autoimmune disorder affecting the central nervous system resulting in demyelination. "The remaining genes included MMP2, a modulator of neuronal precursor activity and cognitive and motor behaviors; CFB, a complement factor altered in neurologic diseases such as multiple sclerosis; and HOXB3, a critical choreographer of neural development." (PMID 38376950, 2024).
myopia (1 paper, 2023). "In this study, we detected significantly higher intraocular levels of complement proteins involved in the classic pathway (C1q, C2, C4 and C4b) and alternative pathway (CFB, CFI, C3b/iC3b) in human eyes with high-myopia or with pathological myopia." (PMID 37448698, 2023).
neuroblastoma (1 paper, 2023). Neuroblastoma (NB) is the most common solid, extracranial childhood tumor. "There was constitutive expression of complement factor B, C3, C5 and C9 in SH-SY5Y neuroblastoma cell lines stably expressing the NOTCH3 receptor." (PMID 37158955, 2023).
oral squamous cell carcinoma (1 paper, 2015). "In the first approach, we have indeed found a higher expression of CFB and C3 proteins using a label-free pseudoSRM analysis of human saliva from Oral Squamous Cell Carcinoma (OSCC) patients in comparison with healthy individuals." (PMID 26540631, 2015).
Peripheral arterial occlusive disease (1 paper, 2022). "Peripheral arterial occlusive disease (PAOD) is one of the primary manifestations of systemic atherosclerosis, and transthyretin and complement factor B are potential markers for monitoring plasma PAOD disease." (PMID 36358920, 2022).
Pleural effusion (1 paper, 2023). The presence of an excessive amount of fluid in the pleural cavity. "In this work, we confirmed the deregulation of CFB, MSLN and CLDN15 on pleural effusions from epithelioid and biphasic PM." (PMID 38067238, 2023).
polycystic kidney disease (1 paper, 2019). A usually autosomal dominant and less frequently autosomal recessive genetic disorder characterized by the presence of numerous cysts in the kidneys leading to end-stage renal failure. "Treatment of an in vitro model of polycystic kidney disease, the OX161 human autosomal dominant PKD renal epithelial cells, with RSV resulted in a dose-dependent decrease in MCP-1, complement factor B (CFB) protein levels, and TNF-α protein level and activity, suggesting reduced inflammation." (PMID 31319485, 2019).
Polypoidal choroidal vasculopathy (1 paper, 2014). The presence of aneurysmal 'polypoidal' lesions in the choroidal vasculature. "The aim of this study was to clarify whether complement component 2 (C2) and complement factor B (CFB) genotypes are associated with subtypes of polypoidal choroidal vasculopathy, such as polypoidal CNV and typical PCV." (PMID 24965207, 2014).
recessive dystrophic epidermolysis bullosa (1 paper, 2018). "High abundance of complement C3, complement factor B (CFB) and complement C4B has been demonstrated in the saliva of OSCC patients, especially in invasive cutaneous squamous cell carcinoma (cSCC) and recessive dystrophic epidermolysis bullosa–associated cSCCs." (PMID 29423024, 2018).
septic arthritis (1 paper, 2016). "In the present study, we compared the susceptibilities to S. aureus septic arthritis of mice lacking C3, complement factor B (fB), and receptor for C3-derived anaphylatoxin C3a (C3aR) using our well-established murine models for S. aureus arthritis." (PMID 26787717, 2016).
Stroke (1 paper, 2022). Sudden impairment of blood flow to a part of the brain due to occlusion or rupture of an artery to the brain. "On the 7th day after the stroke, differences were found between the study group and the control group (group B vs. C) regarding complement factor B (Bf), apolipoprotein A-I (ApoA1), fetuin A, fibronectin (Fn), cytoplasmic tryptophanyl-tRNA synthetase (TrpRS) and ficolin-2." (PMID 35054033, 2022).
upper respiratory tract infections (1 paper, 2020). "We identified significant upregulation of several genes encoding components of the complement system, including C3, CFB, and C1S, uniquely within the CoV-2 dataset, in contrast to other upper respiratory tract infections (at 24 hpi)." (PMID 34786557, 2020).
vasculitis (1 paper, 2023). "Overall, the high fold increases in MASP1 and CFB together with decreased SERPINA5 and increased C9 suggest the role of the lectin and alternate complement pathway in this form of vasculitis." (PMID 37238213, 2023).
viral myocarditis (1 paper, 2025). Myocarditis that is caused by an infection with a viral agent. "Ultimately, four overlapping features, namely, B2M, C3, CFB, and CASP12, were selected as potential biomarkers for viral myocarditis using both algorithms." (PMID 40230577, 2025).
vitamin D deficiency (1 paper, 2023). A nutritional condition produced by a deficiency of VITAMIN D in the diet, insufficient production of vitamin D in the skin, inadequate absorption of vitamin D from the diet, or abnormal conversion of vitamin D to its bioactive metabolites. "The results showed that vitamin D deficiency led to the abnormal expression of CFB, TPM4, C9, ICOSL, and PI16." (PMID 36178657, 2023). "Moreover, vitamin D deficiency resulted in the abnormal expression of 56 differential proteins, among which the expression levels of complement factor B, complement component C9, inducible co-stimulator ligand, and peptidase inhibitor 16 significantly changed with the decrease in vitamin D content." (PMID 36178657, 2023).
ZIKV infection (1 paper, 2023). "Interestingly, results show induction of components of the complement system that were common to both DENV and ZIKV in the brain such as CfB and C3, but C2 and C4a—components of the classical and lectin pathways, were only induced by ZIKV infection." (PMID 37022660, 2023).